AURKB (aurora kinase B)
Diseases named in the same sentence as AURKB in open-access papers (continued):
Sharing a sentence is not in itself a finding about the gene and the disease.
glioblastoma (17 papers, 2012 to 2024). The most malignant astrocytic tumor (WHO grade IV). "Patients with rs2289590 (AURKB) heterozygous AC genotype had a lower risk of glioblastoma multiforme (GBM) development in comparison with the reference AA genotype (OR = 0.54, 95% CI = 0.33–0.88, P = 0.015)." (PMID 34465813, 2021). "AURKB expression has been identified as a prognostic biomarker in glioblastoma, gastric cancer and oral cancer." (PMID 33915740, 2021). "The results of the present study demonstrated that AURKB (rs2289590) and AURKC (rs11084490) polymorphisms reduce the risk of glioblastoma multiforme development." (PMID 34465813, 2021). "Nanoparticles of AURKB siRNA also showed comparable synergistic activity when used in combination with temozolomide in glioblastoma and enhanced survival of orthotopic mouse models of glioblastoma." (PMID 33915740, 2021). "AURKB has also been associated with TMZ susceptibility and aggressive outcomes of glioblastomas." (PMID 26466313, 2015).
neuroblastoma (16 papers, 2014 to 2025). Neuroblastoma (NB) is the most common solid, extracranial childhood tumor. "To investigate the effect of MYCN on mitotic dysregulation and its functional consequences in neuroblastoma cells, we performed siRNA knockdown of AURKB, BUB1, and KIFC1 in MYCN-regulable SHEP21N cells." (PMID 37958555, 2023). "Then, we decided to additionally determine the expression of the N-MYC oncogene and the nearest circle of regulatory genes (SPT16, AURKA, AURKB) whose expression is often elevated in neuroblastoma and remains unstudied in adult patients with AML, including FLT3-ITD mutation carriers." (PMID 37606386, 2023). "The main objective of this work was to quantify the expression of some genes (C-MYC, N-MYC, SPT16, AURKA, AURKB) that are more characteristic biomarkers for neuroblastoma with poor prognosis, but less studied in AML patients, including carriers of FLT3-ITD mutation with high allelic load." (PMID 37606386, 2023). "High AURKB expression was significantly related to poor prognosis in neuroblastoma patients." (PMID 36439516, 2022). "Here, we studied the effects of the pan-aurora kinase inhibitor tozasertib (VX680, MK-0457) and the aurora kinase inhibitor alisertib (MLN8237) that shows some specificity for aurora kinase A over aurora kinase B in a panel of neuroblastoma cell lines with acquired drug resistance." (PMID 25268132, 2014). "Moreover, Aurora kinase B was identified as drug target in neuroblastoma tumour-initiating cells with deregulated BRCA1 signalling." (PMID 25268132, 2014). "A different investigation has demonstrated that AURKB facilitates the development of tumors and carboplatin resistance via controlling the ERK pathway in neuroblastoma cells." (PMID 39787178, 2025). "AURKB formed a complex with APPL1 and TβRI during mitosis and cytokinesis in CRPC cells, as well as in neuroblastoma cells." (PMID 35853811, 2022). "During mitosis and cytokinesis, AURKB–TβRI complexes formed in midbodies in CRPC and KELLY neuroblastoma cells." (PMID 35853811, 2022). "Different aurora kinase inhibitors including the aurora kinase A inhibitors MLN8054 and alisertib (MLN8237), the aurora kinase B inhibitor AZD1152, and the pan aurora kinase inhibitor CCT137690 were demonstrated to display anti-neuroblastoma activity." (PMID 25268132, 2014). "In MNA neuroblastoma, the fatty acid metabolism process is promoted, and lipid metabolism becomes unbalanced due to the increased expression of ACADM and the inhibition of aurora kinase A (AURKA) and aurora kinase B (AURKB)." (PMID 39126035, 2024). "Nevertheless, by analogy with neuroblastoma and other tumors, it can be assumed that some mitotic serine/threonine kinases (AURKA, AURKB) and transcription factors (SPT16) may be involved to maintain increased expression, particularly of the N-MYC oncogene in leukemia." (PMID 37606386, 2023). "To determine whether AURKB, BUB1, and KIF1C are MYCN target genes, we performed ChIP-PCR and demonstrated a 4-to-10-fold enrichment of MYCN binding to the promoter regions in two MYCN-amplified neuroblastoma cell lines." (PMID 37958555, 2023).
colon carcinoma (15 papers, 2012 to 2025). "Previous studies have shown that AURKB is overexpressed in colon cancer, and decreased AURKB leads to activation of caspase 3, as well as decreased Mdm2, c-Myc, pAKT, and cyclin D1." (PMID 38890303, 2024). "The CETSA confirmed that apigenin and kaempferol, the active components of SNL in colon cancer treatment, were able to bind to AURKB." (PMID 36969029, 2023). "Petsalakiet al. discovered that Cdc-like kinases Clk1, Clk2, and Clk4 in human colon carcinoma BE cells and HeLa cells phosphorylate Aurora kinase B at S33, and subsequently Aurora B phosphorylates CHMP4C." (PMID 30542616, 2018). "Because plant-derived flavones inhibit aurora kinase B, we selected 5-methoxy-2-(2-methoxynaphthalen-1-yl)-4H-chromen-4-one (derivative 31), which showed the best half-maximal cell growth inhibitory effect, and tested whether it can inhibit aurora kinases in HCT116 colon cancer cells." (PMID 30562979, 2018). "To explore the role of AURKB in CRC, we first interrogated GEO dataset GSE74602 which compares the gene expression between 30 pairs of colon tumor tissue and corresponding non-cancerous tissue." (PMID 38713155, 2024).
acute myeloid leukemia (14 papers, 2015 to 2025). Acute myeloid leukemia (AML) is a group of neoplasms arising from precursor cells committed to the myeloid cell-line differentiation. "Previous work showing that the AURKB inhibitor, AZD1152, abrogates growth of human acute myeloid leukemia cells and that growth arrest of mouse Raw264.7 macrophages by H. Pylori is associated with downregulation of AURKB are also consistent with our conclusions." (PMID 28228757, 2017). "Furthermore, AURKB overexpression has been implicated in paclitaxel resistance in NSCLC and is associated with poor prognosis in hematological malignancies, such as acute lymphoblastic leukemia and acute myeloid leukemia." (PMID 40710353, 2025). "AURKB selective inhibitor AZD2811 which is formulated as a nanoparticle is currently in clinical trials as monotherapy and in combination to treat acute myeloid leukemia." (PMID 35612714, 2022).
colorectal cancer (13 papers, 2014 to 2025). A primary or metastatic malignant neoplasm that affects the colon or rectum. "Aurora kinase B (AURKB), a key regulator of mitosis, is frequently upregulated in various malignancies, including colorectal cancer (CRC), and is associated with poor prognosis." (PMID 40784984, 2025). "AURKB overexpression results in chromosomal mis-segregation errors, which are hallmarks of cancer, including colorectal cancer." (PMID 36561847, 2022). "Nonetheless, the precise mechanisms through which AURKB regulates the cell cycle and contributes to tumorigenesis as an oncogenic factor in colorectal cancer (CRC) remain unclear." (PMID 38713155, 2024). "Similarly, BOP1 ribosomal biogenesis factor (BOP1) was reported to promote the malignancy of colorectal cancer cells by inducing higher pAURKB at Thr 232 (active form of AURKB)." (PMID 38233848, 2024).
triple-negative breast carcinoma (13 papers, 2017 to 2025). An invasive breast carcinoma which is negative for expression of estrogen receptor (ER), progesterone receptor (PR), and human epidermal growth factor receptor 2 (HER2). "PLK1 and AURKB mediated survivin phosphorylation promotes triple-negative breast cancer proliferation." (PMID 38351178, 2024). "Pavlidis Template Matching was used to identify the genes whose expression correlated with AURKB in triple negative breast cancer." (PMID 36313574, 2022). "While ANP32E, AURKB and BCL11A induce tumor progression in triple-negative breast cancer cells, downregulation of CDK2-AP1 enhances tumor growth through cell cycle regulation." (PMID 37007972, 2023). "Midostarin has been studied in triple-negative breast cancer cells, which lack FLT-3, and it has been identified as an inhibitor of aurora kinase B, leading to cell cycle arrest and apoptosis." (PMID 38132962, 2023). "In addition, AURKB phosphorylates survivin, a member of the apoptosis suppressor protein (IAP) family, thereby regulating the proliferation of triple-negative breast cancer cells." (PMID 38890303, 2024).
non-small cell lung carcinoma (12 papers, 2015 to 2024). A group of at least three distinct histological types of lung cancer, including non-small cell squamous cell carcinoma, adenocarcinoma, and large cell carcinoma. "AURKB inhibition reduced phospho-histone H3 to attenuate acquired resistance to anti-EGFR therapy in non-small cell lung cancer." (PMID 38713155, 2024). "AURKB is a novel drug target for patients with non-small cell lung cancer with gained resistance to the therapy against EGFR." (PMID 34628367, 2021). "In non-small cell lung cancer (NSCLC), AURKB has been shown to be overexpressed and correlated with poorer prognosis of patients." (PMID 31576249, 2019). "Moreover, haspin elimination by CRISPR sensitizes tumor cells to VX680, an Aurora kinase B inhibitor in head and neck squamous cell carcinomas (HNSCC) and non-small cell lung cancer (NSCLC) cell lines." (PMID 36011043, 2022). "To evaluate this hypothesis, we knocked down PRMT1 expression in A549 human non-small cell lung cancer cells that express high levels of PRMT1, and examined phosphorylation levels of histone H3 at serine 10, which is known as a substrate of AURKB." (PMID 26460953, 2015).
pancreatic cancer (12 papers, 2007 to 2025). "FosTg cells were therefore treated with Hesperadin, which was first described as a potent inhibitor of Aurora kinase B in HeLa cells and more recently proved its efficacy to repress pancreatic cancer growth in mice." (PMID 40634321, 2025). "The gene named AURKB is known to suppress proliferation of pancreatic cancer, and KMT2D is also known to be associated with pancreatic cancer." (PMID 29697368, 2018). "As an AURKB inhibitor, the small molecule inhibitor AZD1152 (commercial name barasertib) has demonstrated dose-dependent tumour-suppressive and apoptotic activity in multiple myeloma, lung, breast, colorectal and pancreatic cancer cell lines." (PMID 38287178, 2024). "Molecular analysis of residual tumors treated with MK591 revealed reduced levels of ERK, cyclin D1 and Aurora kinase B proteins, suggesting that targeting 5-Lox by MK591 or similar agents could be a potent strategy for inhibiting pancreatic tumor growth." (PMID 38746674, 2024). "Although PZD has been reported to have antitumor efficacy in pancreatic cancer, there are no previous reports indicating AURKB or KIF20A inhibition as the possible mechanism for its effects." (PMID 34593983, 2023).
clear cell renal cell carcinoma (11 papers, 2019 to 2025). "AURKB affects the proliferation of clear cell renal cell carcinoma by regulating fatty acid metabolism." (PMID 40427174, 2025). "Furthermore, AURKB was found to be expressed at higher levels in clear cell renal cell carcinoma (ccRCC) tissues, suggesting its potential as a promising biomarker in ccRCC." (PMID 38441546, 2024). "In addition, immunohistochemical staining data of 50 cases of renal clear cell carcinoma and its adjacent normal tissues were collected to verify the difference in protein expression of AURKB in the two tissues." (PMID 38898693, 2024). "Aurora kinase B (AURKB) is an important carcinogenic factor in various tumors, while its role in clear cell renal cell carcinoma (ccRCC) still remains unclear." (PMID 31576249, 2019). "However, the functional effects and regulatory mechanisms of AURKB on clear cell renal cell carcinoma (ccRCC) progression remain largely unknown." (PMID 38890303, 2024).
glioma (11 papers, 2010 to 2024). A benign or malignant brain and spinal cord tumor that arises from glial cells (astrocytes, oligodendrocytes, ependymal cells). "The combined upregulation of UBE2C and aurora kinase B (AURKB), an important player in the cell cycle, is associated with a dismal outcome, therapeutic resistance, and reduced overall survival in glioma patients." (PMID 37958776, 2023). "The analysis of Repository for Molecular Brain Neoplasia Data (REMBRANT) revealed strong negative correlation between SIX3 and AURKA and between SIX3 and AURKB in glioma." (PMID 28595628, 2017). "Besides, PPARG is the most significant gene is responsible for all of these diseases and our shared hub genes AURKB and PLK1 are associated with the disease, respectively, stomach neoplasms and glioma." (PMID 38717954, 2024). "Because of striking morphological changes (data not shown) in glioma cells depleted of either aurora kinase A, aurora kinase B, or aurora kinase C, we investigated the function in vitro." (PMID 34058053, 2022). "For instance, Alafateet al. reported that the upregulation of AURKB and UBE2C led to unfavourable outcomes, such as shorter overall survival and therapy resistance, in glioma patients." (PMID 38634120, 2024). "Aberrant expression of AURKB, MPG and SNCB has been observed in cancers of neuronal cell types - gliomas, astrocytomas and medulloblastomas, respectively." (PMID 22087225, 2011). "Aurora kinase B (AURKB) and ubiquitin-conjugating enzyme E2 C (UBE2C) are involved in the tumorigenesis of gliomas and other malignancies, and simultaneously elevated expression of AURKB and UBE2C is strongly correlated with poor prognosis and therapy resistance in glioma." (PMID 32642801, 2020).
lung adenocarcinoma (11 papers, 2019 to 2025). A carcinoma that arises from the lung and is characterized by the presence of malignant glandular epithelial cells. "To further validate the association of identified miRNAs with AURKB in vitro, we tested the protein expression levels of AURKB among 4 lung adenocarcinoma cell lines, including A549, H1299, PC9 and H1975." (PMID 33612479, 2021). "Higher expression of AURKB contributed to significantly worse overall survival (OS, p=0.002) and progression-free survival (PFS, p=0.013), indicating that AURKB is associated with poor prognosis in patients with lung adenocarcinoma." (PMID 33612479, 2021). "Analyses on multiple omics data of lung adenocarcinoma cohort in The Cancer Genome Atlas (TCGA) were performed based on AURKB expression, and demonstrated its association with clinical characteristics and the potential of using AURKB as a biomarker in predicting patients’ survival." (PMID 33612479, 2021). "For example, miR-486-5p has been shown to regulate DNA damage inhibition and cisplatin resistance in lung adenocarcinoma via AURKB." (PMID 39787178, 2025). "To investigate if there was similar sensitivity between LXY18 and AURKB catalytic inhibitors, we utilized the human cervical cancer cell line, Hela, and the lung adenocarcinoma cell line, Calu-6, both of which respond poorly to AURKB small molecule inhibitors." (PMID 37903144, 2023). "Somatic mutation analysis showed that AURKB, CDC20, CENPF, and KNTC1 had different types of mutations in patients with lung adenocarcinoma, and the main type was missense mutation." (PMID 35354488, 2022). "It is worth noting that through somatic mutation analysis, we found that AURKB, CDC20, CENPF, and KNTC1 had different frequencies of mutations in patients with lung adenocarcinoma, and mainly missense mutation type." (PMID 35354488, 2022). "Yoo and colleagues recently showed that AURKA and AURKB confer an “invasiveness signature” in lung adenocarcinoma, indeed their simultaneous inhibition in vitro and in a murine model of lung adenocarcinoma reduced tumor invasion." (PMID 36387232, 2022). "To conclude, this study proved AURKB as a potential prognostic factor and therapeutic target for lung adenocarcinoma treatment and provide a future research direction." (PMID 33612479, 2021). "We further examined the correlation between AURKB expression and the clinical features of the 513 lung adenocarcinoma patients." (PMID 33612479, 2021). "Taken together, these observations provided rational evidence for the prognostic role of AURKB in lung adenocarcinoma." (PMID 33612479, 2021). "In addition, some potential target genes of the quercetin, such as TOP2A, CA4 and AURKB were related to the prognosis of lung adenocarcinoma patients." (PMID 36949111, 2023). "TCGA-LUAD cohort was used to compare the expression of AURKB in lung adenocarcinoma patients." (PMID 33612479, 2021). "As AURKB is high-expressed in lung adenocarcinoma tissues and correlates with more advanced tumor stage, we hypothesized that AURKB might be a prognostic factor in LUAD." (PMID 33612479, 2021). "CCNB2 and AURKB were negatively correlated with B cells, macrophages, myeloid dendritic cells and CD4+T-cell infiltration in lung adenocarcinoma." (PMID 36909154, 2023).
bladder cancer (10 papers, 2015 to 2024). "AURKB was found to be highly expressed and linked to prognosis in patients with bladder cancer." (PMID 39456780, 2024). "Similarly, analysis of expression by RNA-seq in a cohort of 158 bladder cancer patients revealed that elevated expression of AURKB and PLK4 was associated with high-grade disease, in contrast to GAPDH, which was expressed similarly in both grades." (PMID 31142743, 2019). "Knockdown of AURKB resulted in reduced proliferation, migration, invasion, and cell cycle progression in bladder cancer cells." (PMID 39456780, 2024). "AURKB (Aurora kinase B) was increased after MDM2 upregulation induced by lncRNA PVT1 in bladder cancer cells." (PMID 37215134, 2023). "Together, these observations indicate that PLK4 and AURKB/C act redundantly to promote ACM-stimulated cell motility in various cancers and are associated with more aggressive breast and bladder cancers." (PMID 31142743, 2019). "We here demonstrate that a protein arginine methyltransferase PRMT1, which are overexpressed in various types of cancer including lung and bladder cancer, methylates arginine 887 in an Aurora Kinase B (AURKB)-binding region of INCENP both in vitro and in vivo." (PMID 26460953, 2015). "Furthermore, abnormal expression of PLK4, AURKB and DAAM1 is associated with poor outcomes in breast and bladder cancers." (PMID 31142743, 2019). "AURKB interacts with and regulates MAD2L2 expression in bladder cancer cells." (PMID 39456780, 2024). "For example, we found that an L-FFL motif constituted by SNHG12, E2F1, and miR-16, and an M-FFL motif constituted by E2F1, miR-16 and AURKB could form a complex regulation motif by sharing common TF E2F1 and miRNA miR-16, which were highly dysregulated in breast and bladder cancers." (PMID 27322142, 2016).
ovarian carcinoma (10 papers, 2012 to 2022). A malignant neoplasm originating from the surface ovarian epithelium. "Analyses of AURKB showed an association with detrimental OS in stage I/II ovarian cancer to a greater extent than other combinations." (PMID 26992217, 2016). "The overexpression of AURKB has been shown in various human cancers, including ovarian cancer." (PMID 35810383, 2022).
breast tumors (8 papers, 2011 to 2024). "The gene signature associated with high 14-3-3ζ levels in breast tumors encompassed many with functions in mitosis and cytokinesis, including aurora kinase-B, polo-like kinase-1, CDC25B, and BIRC5/survivin." (PMID 21707964, 2011). "In 20 of 22 cases, breast tumors showed markedly increased expression of AURKB compared to normal tissues." (PMID 36313574, 2022).